SNORD81 (Small nucleolar RNA SNORD81 )
Synonyms: LOC124900422
Gene: Small nucleolar RNA gene on chromosome 1 (85,592,280 to 85,592,356, forward strand). Ensembl gene ENSG00000199934.
Gene Ontology:
Biological process: RNA processing
Cellular component: nucleolus
Homologues: Orthologues: chimpanzee SNORD81 (99% identical), rat Snord81 (90% identical), mouse Gm25789 (87% identical), rabbit SNORD81 (87% identical), mouse Gm25802 (84% identical), pig SNORD81 (84% identical), dog SNORD81 (74% identical), guinea pig SNORD81 (74% identical), guinea pig SNORD81 (69% identical), guinea pig SNORD81 (68% identical). Paralogues in human: SNORD81 (86% identical), SNORD81 (75% identical).